TYK2 (tyrosine kinase 2)
Diseases named in the same sentence as TYK2 in open-access papers (continued):
Sharing a sentence is not in itself a finding about the gene and the disease.
tumor (continued). "TCGA data showed improved survival in patients with low TYK2 expression, which is contrary to our expectations, but bulk RNA data do not distinguish between TYK2 expression in tumor cells and stromal cells." (PMID 40991399, 2026). "This AKP clone also readily metastasized to the liver after intrasplenic injection with significantly increased tumor burden in TYK2-/- host mice, but failed to form peritoneal metastases." (PMID 40991399, 2026). "While the frequency of resident and migratory cDC1 and cDC2 immune cells was not changed in the tumor-draining lymph nodes of TYK2-/- host mice, surface expression of MHC-I was reduced in all four cDC subpopulations." (PMID 40991399, 2026). "As expected from the results of the cytotoxicity assays TYK2-mutant tumor-derived CD8+ T cells also show no striking differences in the expression of effector or JAK-STAT genes." (PMID 40025196, 2025). "In addition, we determined the cytolytic activity and the mitochondrial activity of Tyk2−/− and Tyk2K923E CD8+ T cells and NK cells and generated transcriptional profiles of both cell types upon tumor infiltration." (PMID 40025196, 2025). "Similarly, in lung squamous cell carcinoma, CLDN12 appears to promote EMT through activation of the Tyk2/STAT1 signaling pathway, suggesting a mechanistic basis for its contribution to tumor progression." (PMID 40687428, 2025). "Therefore, we determined the transcriptomes of Tyk2-deficient tumor-derived NK and CD8+ T cells and asked whether the observed functional restoration of Tyk2K923E NK cells becomes apparent at the transcriptional level upon exposure to the complexity of the tumor microenvironment." (PMID 40025196, 2025). "For Bd, there was a negative correlation between tumor budding and the percentage of strong pixels for TYK2 (ρ = −0.270, p = 0.0096, Spearman test)." (PMID 39518103, 2024). "All of these drugs are tyrosine kinase inhibitors (TKIs), except for austocystin D. TKIs target the epidermal growth factor receptor (EGFR) and Erb-B2 Receptor Tyrosine Kinase 2 (ERRB2) pathways, which are known to play crucial roles in tumor progression and metastasis." (PMID 37894479, 2023). "Served as family member of non-receptor protein-tyrosine kinases, Janus kinases (JAKs) consists of JAK1, JAK2, JAK3, and tyrosine kinase-2 (TYK2), they behave pivotal roles in cytokine pathways and are closely related to both inflammatory and neoplastic diseases." (PMID 38095643, 2023). "The role of Tyk2 in solid tumors is not well defined and oncogenic as well as tumor-suppressive functions have been reported." (PMID 36185806, 2022). "Notably, the expression of TYK2 was significantly higher in HPV + HNSCC tissues, compared to matched non-tumor tissues." (PMID 36531252, 2022). "Only tumor multiplicity was increased, suggesting that hematopoietic Tyk2 is involved in early immune surveillance of CRC but not in tumor progression." (PMID 36185806, 2022). "Finally, qPCR analysis revealed diminished expression of TYK2 in B-ALL patients at diagnosis compared to that in healthy donors, further stressing the tumour immune surveillance role of TYK2." (PMID 33260630, 2020). "The SIAH2-dependent proteasomal degradation of TYK2 we report here might represent a possibility to reduce aberrant STAT3 signaling and tumor progression." (PMID 24833526, 2014). "Interestingly, subcutaneous injection of murine CRC cancer cells resulted in an increased tumor burden in TYK2-/- but not in TYK2ΔDC host mice." (PMID 40991399, 2026). "However, the difference between the patient cohorts was not very pronounced and analysis of bulk mRNA expression does not distinguish between TYK2 in tumor cells and stromal cells." (PMID 40991399, 2026). "However, using such as dataset, we could show that TYK2 is prominently expressed in a conventional dendritic cell population positive for LAMP3 and CCR7, the chemokine receptor for homing to tumor-draining lymph nodes." (PMID 40991399, 2026).
tumor (continued). "In view of previous research results we speculate that TYK2 can be used as a biomarker for HNSCC and may be involved in the immune infiltration of the HNSCC tumor microenvironment, in addition, TYK2 has an impact on the malignant biological characteristics of HNSCC cells." (PMID 36531252, 2022). "Defective NK cell-dependent tumor growth control in the absence of TYK2 correlates with defects in splenic NK-cell maturation; NK-cell development in the bone marrow is independent of TYK2." (PMID 31936322, 2020). "The same results were obtained for TYK2, and the mRNA levels of JAK3 were significantly increased in STAD during subgroup analyses based on the race, gender, age, H. pylori infection status, histological subtype, tumor grade, individual cancer stage, and nodal metastasis status of patients." (PMID 33083484, 2020). "We show here that the TYK2 tyrosine kinase is expressed in human ALCLs irrespective of ALK status and is essential for tumor cell viability." (PMID 30131584, 2019). "In contrast to previous studies where resveratrol enhanced the function of tumour suppressor PTEN and inhibited activated Akt in tumour cells, resveratrol treatment in this study did not affect expression of JAK1, PTEN, TYK2 and Akt." (PMID 23372833, 2013). "The discrepancy may relate to the lack of information on whether TYK2 is in the tumor or the TME and/or to the lack of distinction between phosphorylated and unphosphorylated TYK2." (PMID 31936322, 2020).
cancer (46 papers, 2002 to 2026). A tumor composed of atypical neoplastic, often pleomorphic cells that invade other tissues. "Staining for PDGFR showed a tendency toward a lower number of cancer-associated fibroblasts (CAFs) in metastases of TYK2-/- host mice, which was significant in TYK2Δhem host mice." (PMID 40991399, 2026). "Activating mutations of TYK2 and formation of constitutively active fusion proteins are key cancer cell-intrinsic drivers of hematopoietic malignancies." (PMID 40991399, 2026). "Intrasplenic injection of AKP organoids into TYK2-deficient (TYK2-/-) host mice was used to investigate cancer cell-extrinsic functions of TYK2." (PMID 40991399, 2026). "We have recently shown that TYK2 suppresses the expression of indolamine 2-3-deoxygenase 1 (Ido-1) in cancer cells, thereby promoting anti-cancer immunity of autochthonous colitis-associated CRC." (PMID 40991399, 2026). "This is a critical issue, as several studies have suggested an association between TYK2-inactivating germline mutations and an increased susceptibility to the development of various types of cancer in humans." (PMID 40991399, 2026). "Remarkably, HSP90 is pivotal for Tyk2 stability and function, where HSP90 suppression following PU-H71 treatment has been reported to cause Tyk2 and inactivation of Tyk2, in various cancer models." (PMID 39564119, 2024). "Second, the primary objective of these analyses was to evaluate safety profiles of TYK2 inhibition and, therefore, we did not include follow‐up assessment of potential pathophysiological mechanisms underpinning an effect of TYK2 inhibition on cancer risk." (PMID 35747941, 2022). "In several cancers, TYK2 gene mutations result in constitutive activation of TYK2 kinase leading to upregulation of downstream STAT signaling." (PMID 35042970, 2022). "Overexpressed thymic stromal lymphopoietin (TSLP) and tyrosine kinase 2 (TYK2) was also associated with worse survival through pan-cancer analysis." (PMID 35874683, 2022). "As shown in other TYK2 mutated cancers, we investigated NPM1–TYK2 fusion kinase hyperactivation and downstream STAT signaling by Western blot analysis." (PMID 35042970, 2022). "Recent genomics, transcriptomics, and proteomics studies have identified tyrosine kinase 2 (TYK2) as an oncogene that is frequently mutated or overexpressed in many types of cancer and metastases." (PMID 34439323, 2021). "In various cancers, TYK2 overexpression or GOF mutations lead to STAT1 or STAT3 activation and upregulation of anti-apoptotic proteins, including B-cell CLL/lymphoma-2 (BCL-2) and myeloid cell leukaemia-1 (MCL-1)." (PMID 34439323, 2021). "Despite involvement of TYK2 in fusion proteins and the presence of activating mutations in some cancers, with the exception of T-ALL, little is known regarding TYK2’s oncogenic functions and downstream effectors." (PMID 30131584, 2019). "From the current evidence, whether TYK2 inhibitor increases the risk of cancer remains undetermined and needs further study, especially in RCTs with a long-term follow-up period." (PMID 36842216, 2023). "It is unclear, however, whether the elevated cancer risk associated with some JAK inhibitors is shared with this novel TYK2 inhibitor." (PMID 35747941, 2022). "Finally, we were unable to compare the effect of genetically‐proxied TYK2 inhibition on cancer risk to that of genetically‐proxied inhibition of other JAK targets which was outside of the scope of this analysis." (PMID 35747941, 2022). "Other studies have linked the contribution of variants in TYK2 with cancers, including BC." (PMID 32973967, 2020). "Furthermore, the inherited Tyk2 allele P1104A, which exhibits impaired kinase activity, was found in patients with solid tumors (lung, breast, stomach, colon, liver) and suggested to be a cancer-associated hypomorph." (PMID 40991399, 2026).
cancer (continued). "However, the intracellular mechanisms by which TYK2 deficiency within cancer cells may promote tumorigenesis in a cell autonomous manner under certain circumstances remains unclear." (PMID 34439323, 2021). "Several studies have shown that TYK2 is a cancer cell-intrinsic oncogenic driver in hematopoietic malignancies." (PMID 40991399, 2026). "To investigate the cancer cell-intrinsic functions of TYK2 in CRLM, we injected CRC organoids with CRISPR/Cas9-mediated Tyk2 deletion into the spleen." (PMID 40991399, 2026). "A meta-analysis in human cancer patients confirmed the requirement for kinase-active TYK2 for a full-blown cancer immunity." (PMID 40025196, 2025). "Aberrant activation of Tyk2 was documented to facilitate a range of abnormal characteristics of cancer cells including abnormal cellular growth and proliferation alongside invasion." (PMID 39564119, 2024). "The immunohistochemical expression of TYK2 was significantly weaker in cancer than in normal control tissues, and its high predictive value allowed its use as a biomarker in the diagnosis of CRC." (PMID 39518103, 2024). "Fluorescence staining for TYK2 revealed higher TYK2 signal intensities in normal intestinal epithelial cells than in cancer cells." (PMID 39518103, 2024). "Then, we observed that the expression of TRAF1 and TYK2 was lower in the cancer tissues than in the adjacent tissues, however, the expression level of MET is the opposite." (PMID 38363947, 2024). "IF showed a significantly higher fluorescence intensity for TYK2 in normal mucosal cells than in cancer." (PMID 39518103, 2024). "From the family of TYK2 inhibitors, JAK inhibitors have been associated with increased risk of certain cancers." (PMID 36842216, 2023). "TYK2 is overexpressed in several types of cancers and promotes the invasion and proliferation of cancer cells." (PMID 36531252, 2022). "Numerous recent studies have indicated that TYK2 acts as an oncogene and promotes the migration, invasion, and metastasis of various cancers, including gastric, liver, colon, prostate, and lung cancers." (PMID 36531252, 2022). "In this study, we initially used the TIMER2 tool for analyzing the expression levels of TYK2 mRNA in pan-cancer samples." (PMID 36531252, 2022). "The findings of these studies suggested that TYK2 inhibitors hold promise for targeted cancer therapy." (PMID 36531252, 2022). "The data from Tyk2ΔHem tumors suggest that deletion of Tyk2 in cancer cells is required for reduced CD8+ T cell infiltration." (PMID 36185806, 2022). "Janus kinases (JaK) are a family of tyrosine kinases (TKs), including JAK1, JAK2, JAK3, and TYK2, and all of their receptors actively participate in the pathogenesis of various human cancers." (PMID 35634509, 2022). "The role of TYK2 in cancer is complex, and some groups have reported an inhibitory role of TYK2 in metastases." (PMID 34439323, 2021). "This review focuses on the growing evidence from genomic and proteomic screens, as well as molecular studies that link TYK2 to cancer prevalence, prognosis, and metastasis." (PMID 34439323, 2021). "These LOF TYK2 variants failed to phosphorylate STAT3 in cells in vitro, and further support the immunosurveillance role of TYK2 in cancer." (PMID 34439323, 2021). "In cancer cells, activation of TYK2 can lead to decreased cell death as well as increased cell growth and invasion." (PMID 34439323, 2021). "In this review, we provide an overview of the screening, molecular, and animal studies that have characterized the role of TYK2 in cancer and metastases, and the potential of TYK2 inhibitors as effective cancer therapies." (PMID 34439323, 2021). "TYK2 has emerged as a pro-survival factor in many types of cancer through stimulation of proliferation and protection from cell death." (PMID 34439323, 2021). "Previous studies showed that TYK2 is overexpressed in several cancer cells and be supposed to a potential therapeutic target." (PMID 33731185, 2021).
cancer (continued). "In some normal and cancer cell types, TYK2 is involved in IFN signaling to induce apoptosis through pro-apoptotic proteins." (PMID 34439323, 2021). "In this review, we discuss the history of TYK2 with an emphasis on the genomic, proteomic, and transcriptomic screens that have led to characterization of the role of TYK2 in cancer and metastases." (PMID 34439323, 2021). "The fascinating challenge to deciphering the impact of TYK2 in inhibiting or promoting cancer growth stems from its amplifier function, which exacerbates the general complexity of the spatial-temporal activities and networked hierarchies in signaling circuits." (PMID 31936322, 2020). "Subsequent analysis of patient samples and cell lines and screening of cancer data sets revealed more than 50 chromosomal TYK2 rearrangements found mostly in hematological, but also in solid cancers." (PMID 31694222, 2019). "Physical interaction of HSP90 with TYK2 was demonstrated in cancer cell lines and confirmed in a proteome-wide assessment of the HSP90 interactome." (PMID 31694222, 2019). "Dysregulated TYK2 activation, aberrant TYK2 protein levels, and gain-of-function (GOF) TYK2 mutations are found in various cancers." (PMID 31694222, 2019). "A comprehensive list of receptors (over-)expressed in various cancer types which allows us to deduce putative upstream signals involved in hyperactivation of TYK2 was compiled recently." (PMID 31694222, 2019). "The molecular contribution of TYK2 signaling and known protein–protein interactions to the hallmarks of cancer were reviewed previously." (PMID 31694222, 2019). "Expression of SOCS3, which has been shown to inhibit JAK1, JAK2, and TYK2, is frequently reduced in cancer cells, thereby leading to a growth advantage." (PMID 31861612, 2019). "In cancer samples or cell lines, TYK2 was found to cooperate with other oncogenic effectors and pathways, such as the RAF/ERK, MAPKs, PIM1/2, and PI3K/AKT/mTOR pathway." (PMID 31694222, 2019). "Inhibition of HSP90 activity in cancer cells results in degradation of client proteins, such as TYK2 and RIPK1, and reduction in NF-κB signaling, STAT3 phosphorylation and ERK activation, the changes seen in DLBCL cells treated with doxycycline." (PMID 26142707, 2015). "However, it is still possible that TYK2 has cancer cell-intrinsic roles at earlier stages of the CRLM invasion-metastasis cascade." (PMID 40991399, 2026). "TYK2 signaling has been extensively studied in various immune, inflammatory and cancer settings." (PMID 40025196, 2025). "The protein level of TYK2 was significantly higher in controls than in cancer tissues." (PMID 39518103, 2024). "Even more pronounced differences in immunoreactivity for this kinase were found by paired t test for the matched slides (with cancer and surgical margin tissues from the same patients); significantly higher expression of TYK2 was observed in the control tissue (p < 0.0001)." (PMID 39518103, 2024). "Two RCTs reported cancer as the possible adverse effect of TYK2 inhibitor." (PMID 36842216, 2023). "Besides, in cancer cells, TYK2 activation can lead to increase cell survival, cell growth, invasion, and resistance to chemotherapy." (PMID 36077723, 2022). "Janus kinase Tyk2 is implicated in cancer immune surveillance, but its role in solid tumors is not well defined." (PMID 36185806, 2022). "TYK2 acts as an oncogene, and its overexpression has been detected in many types of cancer." (PMID 35874683, 2022). "Tyk2 blocks induction of the IFNγ-regulated immune checkpoint Ido1 in Paneth-like cancer cells by an unknown mechanism." (PMID 36185806, 2022). "Both TYK2 and STATs are considered promising targets in cancer and should be tested in SFT." (PMID 36077723, 2022). "TYK2 is required for the immune response to cancer and the development of inflammation." (PMID 34065963, 2021).